IL6 (interleukin 6)
Diseases named in the same sentence as IL6 in open-access papers (continued):
Sharing a sentence is not in itself a finding about the gene and the disease.
diabetes (continued). "The existence of chronic inflammation in diabetes is mainly based on the increased plasma concentrations of C-reactive protein (CRP), fibrinogen, interleukin-6 (IL-6), interleukin-1 (IL-1), and TNFα." (PMID 20634940, 2010). "Recently, a study focusing on sensory ganglia SGCs showed that activated SGCs release more IL-6 and TNF-α after a tissue injury to escalate neuronal hypersensitivity and chronic pain, which reflects that diabetes (i.e., hyperglycemia) triggers cytokine-induced sympathetic inflammation." (PMID 41596372, 2026). "For primary prevention in diabetes, a practical panel could include HbA1c (glycemic control), an inflammatory marker (hs‐CRP or IL‐6), an endothelial marker (sVCAM‐1 or ADMA), kidney function (albuminuria and/or eGFR), and a lipoprotein measure (Lp(a))." (PMID 41567175, 2026). "Even if diabetes does not develop, long-term hyperglycemia is known to increase plasma values of cytokines such as TNF-α, IL-6, and VEGF, causing retinopathy-like changes." (PMID 41578817, 2025). "These included inflammatory cytokines (IL-1α, IL-6 andTNF-α), oxidized LDL (oxLDL) that model the inflammatory environment of atherosclerotic plaques, and metabolic stressors (high glucose and low serum) that reflect diabetic vascular dysfunction." (PMID 41332607, 2025). "There were no significant mean differences between the CI and non-CI groups in IL-6, HbA1c, Self-care of Diabetes Inventory, or Self-rated Abilities for Health Practices Scale." (PMID 39901828, 2025). "Interleukin-6 (IL-6) was assessed in two studies; one showed a significant increase in diabetes, while the other found a non-significant upward trend." (PMID 41150802, 2025). "In people with diabetes, there is often a persistent state of low-grade inflammation, marked by increased levels of pro-inflammatory substances like tumor necrosis factor-alpha (TNF-α) and interleukin-6 (IL-6)." (PMID 41268323, 2025). "These anti-inflammatory and antioxidant effects have been similarly reported in various pathological models, including colitis, ischemia–reperfusion injury, and diabetes, where MB administration reduced TNF-α, IL-1β, IL-6, and CRP levels, suppressed MPO and MDA, and enhanced SOD activity." (PMID 40870501, 2025). "Characterized by chronic low-grade inflammation, diabetes alters the expression of key inflammatory mediators such as monocyte chemoattractant protein-1 (MCP-1), interleukin-6 (IL-6), and C-C motif chemokine receptor 2 (CCR2), which collectively modulate peripheral and central immune responses." (PMID 40831951, 2025). "Elevated levels of serum reactive oxygen species, interleukin (IL)-1, IL-6, tumor necrosis factor (TNF)-α, and C-reactive protein (CRP) have been observed in patients with established type 2 diabetes mellitus (T2DM), indicating their potential role in periodontal tissue destruction." (PMID 40283677, 2025). "This meta-analysis evaluates the effects of probiotics on C-reactive protein (CRP), tumor necrosis factor-alpha (TNF-α), interleukin-6 (IL-6), malondialdehyde (MDA), total antioxidant capacity (TAC), glutathione (GSH), and nitric oxide (NO) in patients with diabetes." (PMID 40123937, 2025). "Higher serum C-reactive protein levels (6.6 ± 12.3 mg/dL, p = 0.04) along with higher levels of pro-inflammatory cytokines IL-6 (1.59 ± 1.19, pg/mL, p = 0.01) and TNF-α (1.49 ± 0.55 pg/mL, p = 0.01) indicated greater systemic inflammation in participants with diabetes." (PMID 40533477, 2025). "Pro-inflammatory cytokines, including IL-6 and TNF-α, and ROS production are increased in both type 1 and type 2 diabetes mellitus, although the degree may be higher in type 1 diabetes mellitus." (PMID 40862723, 2025). "Diabetes worsens periodontitis via ↑ inflammatory response, impaired bone metabolism, oxidative stress, and AGE–RAGE signaling; GLP‐1RAs inhibit NF‐κB and activate AMPK, suppressing IL‐6, IL‐1β, and TNF‐α." (PMID 41328144, 2025).
diabetes (continued). "Eighteen candidate predictors were initially evaluated based on clinical relevance and admission availability: sex, age, smoking history, alcohol consumption, hypertension, diabetes, SAP etiology, BMI, NEUT, PLT, HCT, D-dimer, CRP, IL-6, PCT, SIRS, APACHE II score, and NLR." (PMID 40852356, 2025). "Interestingly, PDB and flavone treatment significantly inhibited diabetes-mediated increase in levels of IL-1β, IFN-γ, TNF-a, and IL-6." (PMID 40486272, 2025). "Elevated IL-6, CRP, and TNF-α levels have been reported in AD patients with diabetes mellitus." (PMID 41294487, 2025). "Unlike the pathological glycogen buildup seen in diabetes, IL-6 KO mice in our study showed lower renal glycogen content than WT littermates." (PMID 40907786, 2025). "Immunologically, type 1 diabetes mellitus patients showed significantly increased counts of T lymphocytes, CD3 + CD8 + T cells and B lymphocytes, along with decreased interleukin-2 and increased interleukin-6 levels compared to healthy controls." (PMID 41455069, 2025). "Patients under the age of 70 with a normal BMI, no diabetes, and smokers are respectively candidates for chemotherapy with gemcitabine due to low IL6 expression." (PMID 40523922, 2025). "Other reports similarly noted that hyperglycemia and diabetes are associated with profound lymphopenia and elevated CRP, IL-6, TNF-α, and PCT compared with non-diabetic patients." (PMID 41156159, 2025). "The age of the control group was lower than that of the NLM group, and the differences between the two groups in terms of age, history of diabetes mellitus, history of dysglycemia, history of smoking, fasting blood glucose, WBC, IL-6, and hs-CRP were statistically significant (P<0.05)." (PMID 40386528, 2025). "Univariate logistic regression analysis identified significant independent predictors of ACS, including age, gender, history of diabetes, smoking history, TGs, TNF-α, IL-6, ceramide (d18:1/16:0), ceramide (d18:1/18:0), ceramide (d18:1/24:0), ceramide (d18:1/20:0) and ceramide (d18:1/22:0)." (PMID 38218768, 2024). "It has also been shown that among patients with peri-implantitis, salivary IL-1β, and IL-6 levels were significantly higher in those with diabetes than in those without diabetes." (PMID 38614881, 2024). "Concerning the group of patients without diabetes it was verified not only positive significant correlations between levels of IL-10 and IL-6 or IFN-γ but also a negative significant correlation between the levels of IL-6 and PMP, at baseline (T0)." (PMID 39253540, 2024). "In the group with diabetes, it was verified positive correlations between IL-10 and IL-6 or IFN-γ and a negative correlation between IL-6 and PMP, at T0; in contrast, in the T1, negative correlations were found between TNF-α and IL-10 or PMP." (PMID 39253540, 2024). "Logistic regression analysis revealed that diabetes mellitus (OR 3.305, 95% CI: 1.866–12.616; p = 0.047), CRP level (OR 1.002, 95% CI: 1.001–1.023; p = 0.044), and IL-6 level (OR 1.045, 95% CI: 1.017–1.063; p = 0.001) were independent risk factors for hypoactive delirium." (PMID 38523173, 2024). "Subsequently, we selected IL6, AKT1 and PPARG as core targets for the treatment of diabetes." (PMID 39707185, 2024). "Patient clinical characteristics and data, including age, gender, body mass index (BMI), hypertension, diabetes mellitus, dyslipidemia, smoking status, levels of C-reactive protein (CRP) and interleukin-6 (IL-6), and ischemic symptoms within 6 months before surgery, were collected retrospectively." (PMID 38167983, 2024).
diabetes (continued). "Mechanistically, diabetes induction resulted in kidney inflammation by elevating levels of tumor necrosis factor-alpha (TNF-α), transforming growth factor beta (TGF-β), and interleukin 6 (IL-6), while reducing IL-10 levels and increasing the IL-6/IL-10 ratio." (PMID 38510054, 2024). "Our findings revealed decreased levels of omentin-1 and increased levels of interleukin-6 in the group with diabetic nephropathy compared to those without diabetic nephropathy among patients with type 2 diabetes mellitus." (PMID 39131026, 2024). "However, during pre-diabetes, oxidative stress has been shown to activate pathways that release pro-inflammatory cytokines such as TNF-α, IL-6 and CRP." (PMID 39596174, 2024). "Serum levels of IL-6 were high in both subgroups of subjects, especially in those with diabetes when compared with those without diabetes (median 518.5 pg/mL, range 0–4966.93 pg/mL vs. median 141.84 pg/mL, range 0–2145.17 pg/mL; p = 0.05)." (PMID 38921685, 2024). "These parameters were then subjected to collinearity analysis, male, age, diabetes, presence of SIRS, bacterial or fungal infections, encephalopathy, ARDS and shock, LDH, amylase, creatinine, troponin I, APTT, IL-6 and viral load were included in the multivariate analysis." (PMID 38291390, 2024). "In diabetes, persistent hyperglycemia leads to “a state of chronic low-grade inflammation, characterized by elevated levels of pro-inflammatory cytokines such as tumor necrosis factor-alpha (TNF-α), interleukin-1 beta (IL-1β), and IL-6." (PMID 39139325, 2024). "In patients with diabetes, carotid PVAT surrounding the atheromatous plaques showed an increase in the mRNA levels of tumour necrosis factor-α (TNF-α), monocyte chemoattractant protein-1 (MCP-1), and interleukin-6 (IL-6)." (PMID 38667739, 2024). "The rest of the patients (one patient with diabetes and six without) had increased IL-6 serum levels, but less than two times the regular value (50–100 pg/mL)." (PMID 38921685, 2024). "Increased levels of CRP, IL-6, and TNF-α were also revealed in patients with both diabetes and MCI." (PMID 38396924, 2024). "Our study findings indicated that levels of omentin-1 were diminished, while IL-6 levels were elevated in the group with DN compared to those with type 2 diabetes mellitus without DN." (PMID 39131026, 2024). "The tendency for the more pronounced cytokine response was observed in patients with T2D compared to patients without diabetes: interleukin-6 (IL-6) level was 8.46 pg/mL [5.08; 14.27] vs. 6.18 pg/mL [4.94; 7.89] accordingly (p = 0.0907)." (PMID 38398069, 2024). "In this context, the exploration of the relationship between IL-6 and DKD is of particular importance, as IL-6 plays a pivotal role in diabetes-related inflammatory responses and may significantly affect kidney structure and function." (PMID 39749325, 2024). "Type 2 diabetes mellitus (T2DM) patients with DN have been observed to have higher levels of IL-6 in the bloodstream than T2DM patients without DN." (PMID 39280507, 2024). "Later (16 weeks) hUC-MSC injection also resulted in reduction of diabetes-associated renal abnormalities and serum TGF-β1 but not of serum IL-6 and TNF-α." (PMID 38443965, 2024). "gingivalisLPS induction may produce apical periodontitis and evaluated the changes in IL-6 and TNF-a expression on macrophages after 14, 28, and 42 days in a diabetes mellitus rat model." (PMID 36599453, 2023). "Furthermore, several studies have found elevated levels of IL6 and TNF-α in patients with insulin resistance and clinically diagnosed diabetes." (PMID 35237941, 2023). "Further, C1M correlated to female sex, age, BMI, triglycerides, non-HDL cholesterol, CRP, diabetes and IL-6." (PMID 37714678, 2023). "Both diabetes and HIV drive elevated levels of C-reactive protein as seen from our results, however, IL-6 could be better marker than CRP for the inflammation seen with diabetes and even in HIV co-morbidity." (PMID 37545969, 2023).
diabetes (continued). "Endogenous irisin levels are lower in obese patients with diabetes, and a negative correlation exists between irisin and the pro-inflammatory cytokine, interleukin-6 (IL-6)." (PMID 38029393, 2023). "It is noteworthy that diabetes is characterized by a pro-inflammatory state, marked by chronically elevated levels of tumor necrosis factor α (TNF-α), transforming growth factor β (TGF-β), and interleukin-6 (IL-6)." (PMID 38137522, 2023). "This observed trend was also noticed in other animal models of high-fat diet or streptozotocin-induced diabetes, where probiotic Lactobacillus plantarum increased the expression of IL-10 while decreasing the expression of TNF-α and IL-6, providing immunomodulatory characteristics of probiotics." (PMID 37894792, 2023). "However, recent studies have demonstrated through biological and proinflammatory analyses of TNF-α, IL-6, CRP and MMP that this cytokine storm condition directly influences systemic conditions or diseases, such as diabetes and CVD." (PMID 36984510, 2023). "Diabetes induced a significant increase in gene expression for Il1β and Il6 compared to ND mice, regardless of genotype." (PMID 37033925, 2023). "Diabetes mellitus can alter the oral microbiota, and this effect is partially reversed only by giving antibodies of inflammatory mediators IL-17, RANKL, and IL-6, which indicates that diabetes mellitus, oral bacterial composition, and inflammation have a strong correlation." (PMID 37664859, 2023). "The main contribution of this research was that diabetes enhances the lung injury and inflammation in rats due to elevated levels of TNF-α, IL-6, and IL-1β and lower levels of IL-10, lower SOD and GPx activity, TAC levels, and increased MDA and NO levels in tissue and BALF." (PMID 37520024, 2023). "For those without diabetes who were not using IL-6 inhibitors, 12 mg/d was more beneficial when using either IMV or NIV/cCPAP than open systems." (PMID 37085591, 2023). "In patients with diabetes and neuropathy, in addition to TNF-α, IL-6 production is increased." (PMID 37686346, 2023). "Next, for both those with and without diabetes, 12 mg/d was less beneficial for patients using IL-6 inhibitors at baseline." (PMID 37085591, 2023). "Moreover, it inhibited diabetes-induced neuroinflammation by decreasing the inflammatory markers NfκB, TNF-α, IL-1β, and IL-6 and downregulating the BDNF/ERK/CREP pathway." (PMID 38105928, 2023). "IL-6 levels are significantly increased in the plasma of patients with DN patients than those with diabetes but without nephropathy." (PMID 36776877, 2023). "Data supporting diabetes-induced microglial phenotype in db/db mice include IL-1β and TNF-α upregulation in the cortex and hippocampus of these mice; as well as higher secretion levels of IL-1β, IL-6, TNF-α and MCP-1 by isolated forebrain mononuclear cells." (PMID 36869375, 2023). "Previous studies have confirmed that the level of cellular inflammatory factors such as tumor necrosis factor-α (TNF-α), interleukin-6 (IL-6) and C-reactive protein (CRP) was increased in elderly patients with diabetes, and anti-inflammatory factors such as IL-10 were reduced." (PMID 38273819, 2023). "As for the molecular mechanism of anti-diabetes, five compounds with better activity in vitro were selected to explore their effects on the AKT1, IL-6 and VEGFA mRNA expression, indicating that their anti-diabetes mechanism was related to PI3K-AKT signaling pathway." (PMID 36559019, 2022). "Our results indicate that ET-1 may play a critical role in mediating myopathy and adipose inflammation through the release of IL-6, TNF-α, or adipokines visfatin through PI3K/Akt/miR-let-7g-5p pathways in elderly individuals with diabetes." (PMID 35468098, 2022). "IL-6 subsequently binds to its receptor (IL6R) on hepatocytes to enhance the production of thrombopoietin, thereby regulating platelet production and resulting in diabetes-induced thrombocytosis." (PMID 35330392, 2022).
diabetes (continued). "Our results uncovered that AS-IV can protect retinal cells against diabetes induced retinopathy, which may act on target proteins AKT1, CASP3 and HIF1α, VEGFA, IL6, IL1β, SRC and CTNNB1, and might be involved in the regulation of PI3K-AKT signaling pathway." (PMID 35814228, 2022). "Patients with diabetes mellitus are in a prolonged chronic inflammatory state, and there is prolific activation of inflammatory cytokines, including tumor necrosis factor α (TNF-α) and interleukin 6 (IL6)." (PMID 36589835, 2022). "Moreover, the ROC curve of the model, combining age, diabetes mellitus, CD3+ T cell count reduction, and IL–6 elevation, had a larger AUC (0.887 [95% CI 0.837–0.937; P < 0.001) with the cutoff value of 0.309 (sensitivity 77.4%, specificity 85.7%)." (PMID 35346253, 2022). "In addition, the oxidative stress produced by diabetes can also produce many inflammatory cytokines, such as TNF-α, IL-6, and transforming growth factor β." (PMID 35669482, 2022). "In particular, we found that serum IGF-1 and IL-6 levels were significantly lower in the control group than in the diabetes without nephropathy group, the macroalbuminuria group and the microalbuminuria group (P < 0.05)." (PMID 36568065, 2022). "In addition, Lcn10-KO macrophages exhibit higher expression of cytokines/chemokines (i.e., IL-6, IL-1β, and CCL2) than wild-type controls, which are also major culprits for the development of cardiomyopathy during diabetes." (PMID 35757735, 2022). "On the other hand, the results derived from standard linear regression, from regression stratified by SB levels, from ISM and from compositional approaches are in disagreement for fasting glucose, 2-h glucose, 2-h insulin, insulin sensitivity, HOMA-IR, incident diabetes, CRP and IL-6." (PMID 35544519, 2022). "Experiments show that GMP can reduce the levels of IL-6, TNF- α, and CRP, increase the level of IL-10, and then alleviate the inflammatory reaction induced by diabetes and repair the phenomenon of hepatocyte lysis and inflammatory cell infiltration in mice, so as to improve the liver injury." (PMID 35399678, 2022). "This research proved significant variations of adiponectin, nesfatin-1, IL-6, and TNF-α levels in the healthy, prediabetics, and T2DM, suggesting a slow and gradual change during the progression from a healthy condition toward diabetes via prediabetes." (PMID 35311231, 2022). "Regular exercises have been shown to increase the release of anti-inflammatory cytokines and they lead to a reduction in pro-inflammatory cytokines, e.g., TNF-α and interleukin 1β (IL-1β), interleukin 6 (IL-6), interleukin 18 (IL-18), CRP, which play a role in the pathogenesis of diabetes." (PMID 36555387, 2022). "We also determined the effect of BA and diabetes on inflammation in wound tissues, and the results showed that diabetes (STZ/VEH) treatment significantly increased mRNA levels of IL1β, IL6 and MCP1; treatment with BA-TOP and BA-IP partly, while BA-IP/TOP treatment completely, reversed this effect." (PMID 35415192, 2022). "At the same time, the mRNA expression of IL-6, ICAM, and TNF-α in retinal tissue began to be highly expressed in the diabetes group on the 8th day after induction, and the difference was statistically significant compared with that in the normal group at the same time point (P < 0.01)." (PMID 35126785, 2022). "However, a statistically significant difference (p-value of less than 0.05) in PI, BoP and PD and in the values of IL-6 and TNF-α was found when a comparison was made between the non-diabetes and prediabetes group." (PMID 36557041, 2022). "It is documented that patients with diabetes, in contrast to non-diabetics, have elevated levels of aqueous and vitreous IL-6." (PMID 35239010, 2022).